CBX2 (chromobox 2)
Diseases named in the same sentence as CBX2 in open-access papers (continued):
Sharing a sentence is not in itself a finding about the gene and the disease.
cancer (continued). "The discovery of USP27X as a deubiquitinating enzyme for CBX2 sheds light on the regulatory mechanisms controlling its stability, providing potential therapeutic targets for aggressive cancers." (PMID 38030604, 2023). "Conversely, the deficiency of USP27X results in CBX2 degradation, indicating a tumor-suppressive role for USP27X in restraining cancer progression." (PMID 38030604, 2023). "The findings showed that CBX2-positive malignant tumors demonstrated significantly elevated levels of stemness rather than CEP55-positive." (PMID 37980163, 2023). "Beta-catenin had been confirmed to aggravate hepatocarcinogenesis and promote cancer stem cell properties, which enforced us to explore the relationship between CBX2, CEP55 and cancer stem cells." (PMID 37980163, 2023). "We discovered that cancer-associated fibroblast (EPIC, MCPCOUNTER) strongly connected with CBX2 and CEP55, consistently with ECM enrichment." (PMID 37980163, 2023). "CBX2, a member of the polycomb group (PcG) complex, plays a pivotal role in tumorigenesis across various cancer types." (PMID 38030604, 2023). "Chromobox protein homolog 2 (CBX2) exerts a multifaceted impact on the progression of aggressive cancers." (PMID 38030604, 2023). "GSEA of genes that correlate with high CBX2 expression in the TCGA PanCancer database for these cancer types shows positive enrichment for E2F target genes and for genes upregulated when expression of RBL2 is low." (PMID 35884550, 2022). "Accumulating evidence suggests that the PRC1 complex member CBX2 is overexpressed in solid tumors and promotes cancer cell survival." (PMID 35681235, 2022). "Further research was needed to investigate the specific function of CBX2 in different types of human cancers by SW2_152F or other CBX2 inhibitors." (PMID 36566204, 2022). "The expression of CBX1, CBX2, CBX5, and CBX8 significantly positively correlates with cancer stemness in LIHC, LUAD, and UCEC tumors, while CBX6—negatively associates with cancer stemness in LUAD and PAAD tumors." (PMID 36361869, 2022). "Our findings also lay the groundwork for future investigations into CBX2-dependent p38 MAPK signaling in multiple cancer contexts." (PMID 35681235, 2022). "The results showed that the mRNA expression levels of CBX2/4/5/8 were significantly correlated with individual cancer stages of OV, and patients who had higher cancer stages tended to express lower mRNA expression levels of CBXs." (PMID 35155439, 2022). "CBX paralogs are frequently misregulated in cancer, with CBX2 and CBX8 as the most commonly upregulated paralogs, and CBX7 and CBX6 as the most commonly downregulated." (PMID 34617019, 2021). "Although CBX2 has been reported to be abnormally expressed in a number of cancer types, the role of CBX2 in CRC remains largely unclear." (PMID 34321009, 2021). "CBX2 is one of the most highly upregulated epigenetic modifiers in the neuroendocrine disease and in cancer cells is required for cellular proliferation." (PMID 33793068, 2021). "The expression of CBX2 in CRC ranked 21th highest among all cancer types, as determined by CCLE analysis." (PMID 34321009, 2021). "Past studies have shown CBX2 activity in cancer to be regulated by miRNAs, and to this list, we add a novel candidate miR‐8485 from PCa cells." (PMID 33793068, 2021). "Our study indicated that mRNA and protein expression of CBX2 were significantly overexpressed in GC compared to normal tissues, while it was also correlated with nodal metastatic status and individual cancer stage in GC patients." (PMID 33344640, 2020). "Although CBX2 has been less-studied in cancer research, the molecular profile of CBX2 suggested that it plays an oncogenic role." (PMID 31321712, 2019). "While the functional role of some CBX proteins in cancer has been largely described, recent reports support the specific role of CBX2 in human tumors." (PMID 29467492, 2018).
cancer (continued). "CBX2 upregulation and amplification significantly correlated with metastatic progression and lower overall survival in many cancer types, particularly those of the breast." (PMID 29190923, 2017). "Taken together, this study provides the first evidence that CBX2 inhibition induces cancer cell death, positioning CBX2 as an attractive drug target in lethal CRPC." (PMID 26877821, 2016). "In conclusion, this study provides the first evidence that the H3K27me3 reader CBX2 is functionally involved in any human cancer, thereby adding to the growing landscape of cancer epigenetics." (PMID 26877821, 2016). "We have previously demonstrated that CBX2 expression was significantly up-regulated in aggressive tumors of many cancer types, including PCa." (PMID 26877821, 2016). "Despite playing imperative roles during embryonic development, CBX2 has been overlooked for many years in the cancer literature." (PMID 25859291, 2015). "Moreover, the Ki67 level was considerably increased in the CBX2 OE tumors, indicating increased cancer cell proliferation." (PMID 39793896, 2025). "Among the CBX family members, CBX2 stands out for its significant impact on cancer biology." (PMID 40175347, 2025). "As the overexpression of CBX2 is closely correlated with a poor prognosis for tumours, CBX2 is expected to be a potential promising therapeutic target for cancer gene therapy." (PMID 39114365, 2024). "For example, CBX2 could drive a cancer stem cell-like phenotype in HCC revealed by multi-omics and multi-cohorts." (PMID 38702698, 2024). "Additionally, CBX2 expression in cancer tissues was higher than normal tissues and escalated CBX2 expression was significantly correlated with tumor size, lymph node metastasis, and high TNM stage." (PMID 38702698, 2024). "CBX2 may contribute to cancer progression through ceRNA networks, suggesting that it is a promising therapeutic target for cancer." (PMID 38355480, 2024). "According to this research, CBX2 could control CEP55 or CTNNB1 to control the characteristics of cancer stem cells that are consistent with more aggressive migration." (PMID 37980163, 2023). "Furthermore, through functional enrichment analysis, we found a significant correlation between four signature genes (CBX2, LDHA, SPP1, and ZC4H2) and malignant tumor biology, exhibiting upregulation in high-risk patients." (PMID 37287752, 2023). "Additionally, CBX2 promotes epithelial-mesenchymal transition (EMT), which is associated with increased invasive and metastatic potential of cancer cells." (PMID 38030604, 2023). "Furthermore, to confirm the clinical significance and therapeutic potential of targeting USP27X and CBX2 in cancer treatment, more extensive clinical studies and functional preclinical studies are required." (PMID 38030604, 2023). "Interestingly, CBX2 exhibits both tumor suppressive and promoting functions depending on the specific cancer type." (PMID 38030604, 2023). "CBX2 showed a highly positive correlation with CEP55 at pan-cancer level." (PMID 37980163, 2023). "The lowest mRNA expression levels of CBX2/4/5/8 were detected in cancer stage 4." (PMID 35155439, 2022). "Studies have shown that Cbx2 knockdown reduced cancer cell proliferation, migration, and invasion." (PMID 36109779, 2022). "We show that functioning CBX2 is crucial for cancer cell growth and viability." (PMID 35884550, 2022). "Evidence suggests that CBX2 may play a more prominent role in cancer progression compared to other CBX paralogues." (PMID 35884550, 2022). "CBX2/4/5/8 were significantly correlated with individual cancer stages of OV." (PMID 35155439, 2022). "Although ER+ve disease has targeted therapeutic options, many cancers become resistant to first-line therapy; therefore, additional target proteins, such as CBX2, could still be efficacious in treating this BCa subtype." (PMID 35884550, 2022). "For instance, in many cancers CBX2/CBX8 are oncogenic while CBX6/CBX7 are tumor suppressive." (PMID 34617019, 2021).
cancer (continued). "CBX2 inhibition could induce cancer cell death, and CBX2 was positioned as a drug target in lethal castration-resistant PCa (CRPC)." (PMID 34568039, 2021). "Another article found that CBX2 is also the only CBX protein with a DNA binding domain 37, which is associated with modulating transcription of target genes and binding to other PRC1 components and is involved in the development of human cancer." (PMID 32742466, 2020). "Anyway, we observed a significant down-regulation of CBX2 in optimal responder patients: this gene has been reported to play an oncogenic role, with its up-regulation being able to predict progression and shorter OS in multiple cancer types." (PMID 31293972, 2019). "Nevertheless, different chromatin-modulating drugs such as histone deacetylase inhibitors (HDACi) are reported to regulate CBX2 targets on chromatin, suggesting that HDACi might be used to indirectly modulate aberrant effects of CBX2 in cancer." (PMID 29467492, 2018). "Besides, over-expression and amplification of CBX2 were significantly related with metastatic progression and shorter OS in many cancer types, particularly in BC patients." (PMID 30481161, 2018). "In line with several studies reporting that CBX2 was a potential drug target in human cancers." (PMID 29190923, 2017). "Interestingly, we found that cancer was the disease most significantly linked to CRGs, in line with our previous finding that CBX2 is involved in a wide range of cancer types." (PMID 26877821, 2016). "Additionally, our results suggested that CBX2 could promote cancer cell proliferation both in vivo and in vitro." (PMID 39793896, 2025). "Furthermore, the involvement of CBX2 in ceRNA networks has been reported in diverse cancer types." (PMID 38355480, 2024). "In addition, CBX2 and CEP55 may enhance extracellular matrix reprograming via cancer-associated fibroblast." (PMID 37980163, 2023). "Therefore, overexpressing CBX2 and CEP55 may cause cancer cells to develop cancer stem cell-like phenotypes with high levels of invasion, metastasis, and radiation resistance." (PMID 37980163, 2023). "Consistently, our study provided evidence that knockdown of CBX2 could simultaneously alleviate two pro-cancer histone modification (H3K27me3 and H2AK119ub), and this therapeutic strategy may especially benefit HCC patients who bear an aberrant epigenetic landscape like subtype Group A patients." (PMID 36566204, 2022). "While further investigation is required, these data do suggest that CBX2 may inhibit the expression of the tumour suppressor RBL2 in multiple cancer types and, therefore, may repress RBL2-DREAM complex activity across multiple malignancies to promote cell growth." (PMID 35884550, 2022). "Secondly, CBX2 positively regulates genes of the MAPK signaling pathway, enhancing cancer cell proliferation and promoting cell migration." (PMID 40175347, 2025). "Additionally, CBX2 may also influence the sensitivity of cancer cells to chemotherapeutic drugs." (PMID 38355480, 2024). "To understand the impact of CBX2 on the TIME of human HGSC tumors, we next examined the data derived from TCGA and the Carcinoma EcoTyper." (PMID 38984891, 2024). "Furthermore, CBX2 or CEP55 could potentially serve as therapeutic targets for pan-cancer." (PMID 37980163, 2023). "Surprisingly, we performed the differential gene analysis in another 20 cancers and found CBX2 and CEP55 up-regulated in 16 and 18 of 20 cancers." (PMID 37980163, 2023). "A literature survey about significant biomarkers highlighted in survival analysis revealed that GNG11, CBX2, CDKN3, ARHGEF10, CLN8, SEC61G and PTDSS1 genes present similar survival and prognostic behaviors in the specified cancers." (PMID 37489460, 2023). "However, further investigations are necessary to identify specific ubiquitination sites on CBX2, explore potential interactions with other deubiquitinating enzymes, investigate downstream signaling events, and extend the scope of this research to other types of cancer." (PMID 38030604, 2023).
cancer (continued). "We also observed that several CBX members are frequently amplified in cancer tissues, especially CBX1, CBX2, CBX3, CBX4, and CBX8 in LUAD and LIHC tumors." (PMID 36361869, 2022). "Among them, seven genes of CDCAs (CDCA1/NUF2: P = 2.73E-22, CDCA2: P = 1.52E-16, CDCA3: p = 1.50E-20, CDCA5: P = 1.77E-20, CDCA6/CBX2: P = 6.87E-19, CDCA7: P = 5.92E-16, and CDCA8: P = 1.67E-18) were all up-regulated in 19 cancer datasets." (PMID 33665158, 2020). "CBX2 and neural EGFL-like 2 (NELL2) have been shown to promote invasion, metastasis, or cell division in a variety of in vivo and in vitro models of cancer." (PMID 30820027, 2019). "Chromobox 2 (CBX2), a polycomb repressor complex subunit, plays an oncogenic role in other cancers, but little is known about its role in HGSOC." (PMID 30478317, 2018). "Interestingly, CBX2 KD significantly hampers LUAD cell growth and metastasis in cancer cells in vivo." (PMID 40175347, 2025). "In the work described, we observed that indirect co-culture of CBX2 expression in cancer cells led to the increase of CD163- and CD206-expressing TAM, highlighting the contribution of secreted factors from the cancer cells regulating the macrophage phenotype toward tumor promotion." (PMID 38984891, 2024). "In conclusion, our study demonstrated that CBX2 is a vital tumor suppressor in CRC and could be a promising anti-cancer therapeutic target." (PMID 38495501, 2024). "Functionally, CBX2, which was highly correlated with CD44, shaped a cancer stem cell-like phenotype by positively regulating cell-cycle progression, proliferation, invasion, metastasis, wound healing, and radiation resistance, revealed by combining bulk RNA-seq and scRNA-seq datasets." (PMID 37980163, 2023). "Different types of cancer may present unique molecular characteristics and signaling pathways, thus the impact of USP27X and CBX2 could vary." (PMID 38030604, 2023). "Next, we computed the PCC between CBX2 and CEP55 to validate their positive regulatory relationship across cancers and confirmed that a significantly positive correlation greater than 0.2 was observed in 27/33 cancers, especially in THYM." (PMID 37980163, 2023). "Intriguingly, we found that CBX2 and CEP55 expressed more in para-cancerous tissue in GSE25097 compared to healthy tissue, suggesting that abnormally expressed CBX2 and CEP55 may be responsible for the development of cancer." (PMID 37980163, 2023). "At the level of all cancers, we noticed that CBX2 and CDKN1A exhibited a negative trend, strengthening CBX2’s ability to regulate the cell cycle." (PMID 37980163, 2023). "We then investigate CBX2 and CEP55’s effects on cancer-related functional states." (PMID 37980163, 2023). "Therapeutic inhibition of CBX2 could therefore repress mTORC1 activation and promote DREAM complex-mediated senescence in TNBC and could have similar effects in other cancer types." (PMID 35884550, 2022). "Notably, among the deregulated genes observed following CBX2 silencing we also found key genes functionally involved in MAPK pathway, whose activation was extensively shown to play a role in cancer progression." (PMID 35681235, 2022). "While many cancer-specific alterations in PcG subunits are related to specific developmental pathways or cancer-specific phenotypes, some sets of paralogs are universally up and downregulated across multiple cancers, including EZH2/EZH1, RING1B/RING1A and (CBX2/CBX8)/(CBX6/CBX7)." (PMID 34617019, 2021). "In our study, significantly higher mRNA and protein expression of CBX2 were found in HCC tissues, and mRNA expression of CBX2 was remarkably correlated with patients’ individual cancer stages and tumor grades, which were similar to the findings of Clermont’ studies." (PMID 30481161, 2018).
cancer (continued). "According to our comprehensive bioinformatics results, we hypothesized that transcription factor CBX2 regulated ASPH may well be correlated with the carcinogenesis, cancer development, and unfavorable prognosis of KIRP through activation of Notch signaling pathway." (PMID 38702698, 2024). "To further validate whether CBX2 and CEP55 affect malignant cell stemness, we reanalyzed the public datasets related to HCC CSC and observed that CBX2 and CEP55 levels were higher in cancer stem cells that were CD133, ALDH, or CD44-labeled." (PMID 37980163, 2023).